SCD (stearoyl-CoA desaturase)
Diseases named in the same sentence as SCD in open-access papers (continued):
Sharing a sentence is not in itself a finding about the gene and the disease.
type 2 diabetes (41 papers, 2010 to 2025). "Conversely, a higher 5-year risk of developing type 2 diabetes was related to the ratios of palmitoleic acid to palmitic acid and oleic acid to stearic acid, which indicate elevated expression of stearoyl CoA desaturase-1 (SCD1)." (PMID 39940428, 2025). "Interestingly, OM-3CA decreased SCD-1 and δ-6 desaturase indices, but increased δ-5 desaturase index, an apparent enzyme activity pattern that has been associated with reduced risk of developing type 2 diabetes." (PMID 29971527, 2018). "Importantly, SCD gene expression was lower in beta cell enriched tissue (obtained by laser capture microdissection) from individuals with type 2 diabetes compared with healthy donors." (PMID 31796987, 2020). "However, SCD-1 mRNA expression in adipose tissue from subjects with type 2 diabetes was increased after treatment with rosiglitazone." (PMID 26061913, 2015). "In subjects with Type 2 diabetes, increases in plasma NEFA and stearoyl-CoA desaturase (SCD) activity, and reductions in peroxisome-dependent synthesis of very long chain (≥22 carbon) PUFAs (VLCPUFAs) were observed." (PMID 23144998, 2012).
melanoma (39 papers, 2015 to 2026). A malignant, usually aggressive tumor composed of atypical, neoplastic melanocytes. "We show here that elevated expression of key DNFA enzymes such as SCD is associated with poor prognosis in cancers, including melanomas." (PMID 31316083, 2019). "Taken together, these results suggested that inhibition of USP22 enhances ferroptosis sensitivity by downregulating SCD, thereby contributing to the reduction of melanoma metastasis." (PMID 39135915, 2024). "Lorlatinib, an FDA-approved inhibitor primarily targeting ALK/ROS1 tyrosine kinases, is under investigation for its impact on stearoyl-CoA desaturase (SCD) expression in melanoma cells." (PMID 38562143, 2024). "We observed that AML samples clearly dichotomized in sensitive and resistant to SCD inhibition, a pattern also observed in glioblastoma and melanoma." (PMID 39187579, 2024). "All in all, this interfered with NK cell cytotoxicity against melanoma cells and, consequently, inhibition of SCD efficiently restored impaired NK cell killing of NGFRhigh tumor cells in vitro and in vivo." (PMID 36638181, 2023). "Mechanistically, NGFR leads to down-regulation of NK cell activating ligands and simultaneous up-regulation of the fatty acid stearoyl–coenzyme A desaturase (SCD) in melanoma cells." (PMID 36638181, 2023). "By blocking SCD, we were able to restore NK cell killing of NGFR-overexpressing melanoma cells in vivo, as reflected by a notable loss of MF438-treated NGFR-overexpressing cells in mice engrafted with human NK cells." (PMID 36638181, 2023). "We propose that one mechanism by which SCD mediates melanoma cell protection from NK cell killing is by reducing surface expression of CD112 and CD155." (PMID 36638181, 2023). "Most of the enzymes associated with fatty acid synthesis (e.g., FASN, SCD, ACC, ACLY), and receptors related to lipid uptake (e.g., FAT/CD36, FATPs, and FABPpm) are upregulated in several cancers, including melanoma." (PMID 35406721, 2022). "The effect of SCD inhibition on melanoma cells was largely reversed by the addition of the C18:1 or C16:1 MUFA to complement the lack of SCD activity." (PMID 35342344, 2022). "By promoting the conversion from saturated fatty acids to mono-unsaturated fatty acids, SCD upregulation is required for highly-expressed MITF-driven melanoma cell proliferation." (PMID 34924562, 2021). "Stearoyl-CoA desaturase (SCD1) is involved in the conversion of saturated to MUFAs in melanoma cells." (PMID 34649956, 2021). "The authors observed the downregulation of both MITF and SCD in melanoma cells following glutamine deprivation with an alteration of the balance of saturated fatty acids and MUFAs." (PMID 33202944, 2020). "Our studies indicate that Mov10 shRNA increases expression of FASN and SCD in cultured melanoma cell lines promoting Wnt5a secretion." (PMID 26029828, 2015). "Previously, we reported that inhibition of PI3K/Akt/mTOR pathway‐mediated SCD expression could sensitize melanoma to ferroptosis." (PMID 39135915, 2024). "In yet another study, the influence of differential lipid metabolism on therapeutic resistance in 2-D and 3-D systems was determined using GC–MS; the results demonstrated a significant correlation between the expression of stearoyl-CoA-desaturase (SCD1) and the progression of BRAF-mutated melanoma." (PMID 38461268, 2024). "We have previously reported that inhibition of the PI3K/Akt pathway could sensitize melanoma to ferroptosis via downregulating SCD." (PMID 39135915, 2024). "In particular, NGFR-driven expression of stearoyl–coenzyme A desaturase 1 (SCD), which catalyzes a rate-limiting step in the synthesis of unsaturated fatty acids, increased melanoma cell membrane fluidity and hampered the surface expression of NK cell activating ligands such as CD112." (PMID 36638181, 2023). "Thus, proliferative melanoma cells display high activity of enzymes involved in fatty-acid biosynthesis, including SCD." (PMID 35406721, 2022).
melanoma (continued). "As expected, both GBM and melanoma cells acquired resistance to the SCD inhibitor." (PMID 33568479, 2021). "We asked whether the expression of FASN or SCD also correlated with Mov10 expression in human melanoma tumors." (PMID 26029828, 2015). "Moreover, the reduction in MUFA (18:1 n-9 and 16:1 n-7) and the marked decrease in the 18:1 n-9/18:0 ratio value observed in melanoma cells treated with both flavones could be due to an inhibition of SCD." (PMID 38541630, 2024). "Therefore, one potential mechanism of increased dependency on FADS2-mediated fatty acid desaturation in MITFlow/AXLhigh LD-rich melanoma cell lines could be a compensatory mechanism due to reduced MITF-regulated SCD." (PMID 37849907, 2021). "A study identified that a low‐oleic acid diet, when combined with an SCD inhibitor, effectively suppressed tumor growth and metastasis in PTEN wild‐type melanoma models while enhancing the efficacy of anti‐PD‐1 immunotherapy." (PMID 39494561, 2024). "Mining of a SOX10 KD dataset identified MITF, SCD, and MYC as being downstream SOX10 effector genes in this melanoma phenotype." (PMID 38994683, 2024). "Altogether, these observations suggest that a therapeutic strategy that combines SCD inhibition and CD36 blockade would be very effective to refrain phenotypic plasticity in melanoma." (PMID 35406721, 2022). "Of the many changes that affected gene expression, SCD itself was found to be highly up-regulated in AqR cells—an effect noticeably consistent between GBM and melanoma cells." (PMID 33568479, 2021). "To validate the presence of unsaturated fatty acids in LDs, we treated LD-rich melanoma cells with desaturase inhibitors, CAY10566 and SC26196, for inhibiting Stearoyl-CoA desaturase-1 (SCD) and FADS2, respectively." (PMID 37849907, 2021). "In addition, low SCD activity leads to ER stress and inflammatory signaling (Via ATF4 and NF-κB), further suppressing MITF and enhancing melanoma cell plasticity and metastasis." (PMID 41596686, 2026). "In contrast, impaired NK cell killing of NGFR-overexpressing cells could almost completely be rescued by treating NGFRhigh melanoma cells with MF438, an inhibitor of the fatty acid desaturase SCD." (PMID 36638181, 2023). "We are uncertain at this point whether this pathway is active in the SCD inhibitor–resistant GBM and melanoma lines." (PMID 33568479, 2021). "Importantly, our TCGA database analysis indicates that while SCD is expressed at similar levels, FADS2 expression is significantly upregulated in metastatic melanoma compared to primary melanoma." (PMID 37849907, 2021). "Moreover, low activity of stearoyl-CoA desaturase (SCD), which catalyzes the rate-limiting step of FA desaturation, reduced MITF expression and maintained melanoma cells in an MITF-low de-differentiated state." (PMID 33121001, 2020). "Four DNFA enzymes – SCD, FASN, ACLY and ACSS2 – exhibit the highest levels of mRNA expression in skin cutaneous melanoma (SKCM) compared to other tumor types, whereas expression of ACACA is less elevated in melanomas." (PMID 31316083, 2019). "However, high doses of individual pharmacological inhibitors of SCD and FASN enzymes were reportedly required to impact cell viability in melanomas and other cancers." (PMID 31316083, 2019). "Finally, we explored the relationship between USP22 and melanoma vulnerability to ferroptosis and found that USP22 inhibition sensitizes melanoma to RSL3‐induced ferroptosis through inhibiting PI3K/Akt/mTOR pathway‐mediated SCD expression." (PMID 39135915, 2024). "Mechanistically, low SCD expression and activity promoted ER stress and the phosphorylation of eukaryotic initiation factor-α (eIF2α) leading to the activation of an ATF4- and NF-κB-dependent inflammatory signaling that sustains a reduced MITF expression and melanoma cell dedifferentiation." (PMID 33121001, 2020).
atherosclerosis (38 papers, 2010 to 2025). A disease characterized by the build-up of fatty material and calcium deposition in the arterial wall resulting in partial or complete occlusion of the arterial lumen. "Nevertheless, SCD deficiency leads to atherosclerosis under hyperlipidemic conditions, accelerating vascular calcification." (PMID 36982607, 2023). "Remarkably, SCD inhibition has a protective effect on atherosclerosis that is induced by chronic intermittent hypoxia." (PMID 36982607, 2023). "In the search for pathomechanisms, we found up-regulation of an enzyme, stearoyl-CoA desaturase 1 (Scd1), in different experimental models of heart failure induced by advanced atherosclerosis, chronic pressure overload, and/or volume overload." (PMID 34576047, 2021). "This suggests that the ability of SCD-1 to metabolize an increased intake of dietary SFA is critical in order to prevent atherosclerosis." (PMID 20565855, 2010). "Thus, impaired SCD activity is involved in the development of atherosclerosis by modifying blood lipid composition and affecting the metabolism and signaling pathways of cells that form vessels." (PMID 36982607, 2023). "Furthermore, SCD-1 deficiency in mice abolished the IH-induced increased hepatic SCD-1 and plasma VLDL-C levels and atherosclerosis in the ascending aorta." (PMID 36359273, 2022). "Interestingly, in our previous study of leonurine on the treatment of atherosclerosis, we found that leonurine suppressed gene expression of fatty acid synthesis, such as SCD-1 and SREBF in liver tissues." (PMID 36291721, 2022). "Furthermore, some studies have suggested that a reduction in Stearoyl Coenzyme Desaturase-1 (SCD-1) activity, which is responsible for the unsaturation of palmitate (16:0) and stearate (18:0), may contribute to atherosclerosis." (PMID 40176064, 2025). "Thus, SCD inhibition may be protective or detrimental, depending on the mechanism of atherosclerosis development." (PMID 36982607, 2023). "Moreover, mice in which SCD is inhibited and SCD‐knockdown mice have increased atherosclerosis." (PMID 31965762, 2020). "While such data suggests a decrease in SCD-1 activity may be beneficial for weight management, emerging research indicates this reduction may also contribute to atherosclerosis; thus reinforcing that maintaining a balance in SCD-1 activity is paramount to optimize health." (PMID 20565855, 2010). "Stearoyl CoA desaturase 1 (SCD1) deficient mice, although protected from high-fat diet-induced insulin resistance, accumulate macrophage plasma membrane SFA, exhibit greater susceptibility to atherosclerosis, and are hypersensitive to inflammatory stimuli including those signaling through TLR4." (PMID 20814545, 2010). "Stearoyl-CoA desaturase (SCD) is an endoplasmic reticular enzyme in the cell, biosynthesize MUFA from saturated fatty acid (SFA) and effects on key physiological variables especially in metabolism and atherosclerosis." (PMID 30943799, 2019).
hyperlipidemia (28 papers, 2010 to 2026). "Citrus flavonoids, including hesperetin were shown to suppress gene expression of stearoyl-CoA desaturase, an enzyme whose inhibition reduces hyperlipidemia and adiposity." (PMID 37697354, 2023). "These energy storage molecules are also elevated in a hyperlipidemia mouse model that overexpresses SCD." (PMID 24935936, 2014). "One possible mechanism underlying these physiological effects is reduction of hepatic levels of the mRNA for stearoyl-CoA desaturase-1 (SCD1), since repression of this enzyme reduces hyperlipidemia and adiposity." (PMID 21345233, 2011). "However, significantly decreasing of liver lipogenic genes FAS, ACC, SREBP-1c, and SCD-1 were observed when treated with ICAC in hyperlipidemia mice." (PMID 35959429, 2022). "This suggests that SCD-1 may play a role in mediating carbohydrate-induced lipemia; therefore future research that analyzes SCD-1 activity within this context is warranted." (PMID 20565855, 2010). "Our studies using HFD-induced hyperlipidemia animal model revealed that SREBB decoy ODN inhibited the increased expression of fatty acid synthetic pathway, such as SREBP-1c, FAS, SCD-1, ACC1, and HMGCR." (PMID 31952262, 2020). "However, the activation of LXR promoted the transcription of liver lipid synthesis related genes like SREBF1, FASN, SCD, and ACACA, leading to liver steatosis and hyperlipidemia." (PMID 39645039, 2024). "JWFT normalized hepatic fatty acid composition of hyperlipidemia rats by up-regulating hepatic acetyl-CoA carboxylase (ACC), stearoyl-CoA desaturase 1 (SCD1) and fatty acid synthase (FAS) gene expression, and down-regulating carnitine palmitoyl transferase-1 (CPT1)." (PMID 25055996, 2014).
liver cancer (25 papers, 2013 to 2025). An epithelial or non-epithelial malignant neoplasm that arises from the liver. "Certain cancer types, including lung and liver cancers, circumvent the SCD-dependent fatty acid desaturation pathway during proliferation to produce monounsaturated fatty acid." (PMID 40535804, 2025). "SCD is overexpressed in different cell lines including liver cancer cell lines such as Hep3B.SCD utilizes cytochrome b5 electrons and oxygen for fatty acid biosynthesis and is linked to insensitivity to ROS induced apoptosis in certain cancers." (PMID 36680249, 2023). "A recent study showed the presence of a SCD-independent lipid desaturation pathway in some lung and liver cancer cell lines." (PMID 33568479, 2021). "The tumor environment such as fibrosis, hypoxia, dysregulated metabolism might also influence the liver cancer cell regulation of SCD and FADS2 enzyme activities especially in the case of HCC developed from NASH stage." (PMID 31717414, 2019). "The inhibition of stearoyl-CoA desaturase (SCD), FASN and ACC, which provide FFAs within hepatocytes, abrogated Akt-driven HCC and reduced the hepatic cancer stem cells (CSC) pool." (PMID 33920670, 2021). "Elevated expression of SCD and FASN in cancer cells is related to markedly worse prognosis in many human cancers, including liver cancer." (PMID 31083642, 2019). "In liver cancer cell lines, sorafenib reduces the expression of oncoprotein hepatitis B X-interacting protein (HBXIP), thereby inhibiting SCD activation induced by the transcription factor ZNF263, leading to the accumulation of free FAs and the occurrence of ferroptosis." (PMID 41421797, 2025).
glioblastoma (21 papers, 2020 to 2025). The most malignant astrocytic tumor (WHO grade IV). "In contrast, reduced SCD expression was observed in glioblastoma tumors, which increased under nutrient-deficient conditions in glioblastoma cells." (PMID 40430008, 2025). "Insulin is a known regulator of SCD expression, and sensitivity to SCD inhibition in glioblastoma has been linked to increased ERK phosphorylation, also a downstream target of RTK signaling." (PMID 39187579, 2024). "Increased or high expression of SCD is associated with the growth and proliferation of glioblastoma cells." (PMID 37046844, 2023). "Another cause of reduced SCD expression in glioblastoma is the hypermethylation of DNA fragments responsible for regulating the expression of this enzyme." (PMID 37046844, 2023). "Therefore, SCD inhibitors increase the susceptibility of glioblastoma cells to TMZ." (PMID 37046844, 2023). "The SCD-1 inhibitor, A939572, was included in a preclinical trial of glioblastoma and renal cell carcinoma." (PMID 39920872, 2025). "Another case–control study examined the expression of desaturases (FADS1, FADS2, and SCD) in glioblastoma tumors from 28 patients." (PMID 40430008, 2025). "SCD is also important for the functioning of glioblastoma cancer stem cells, particularly for their stemness, and is responsible for TMZ resistance." (PMID 37046844, 2023). "Reduced expression of SCD or its inhibition induces endoplasmic reticulum (ER) stress and cell death in glioblastoma." (PMID 37046804, 2023). "Subsequently, we show that recurrent patient-derived glioblastoma cells can be re-sensitized to TMZ either by supplementing the fatty acid palmitate to media or by targeting SCD or FADS2." (PMID 36338708, 2022). "Here, we report the unexpected finding that median expression of SCD is low in glioblastoma relative to normal brain due to hypermethylation and unintentional monoallelic co-deletion with phosphatase and tensin homolog (PTEN) in a subset of patients." (PMID 33568479, 2021). "We initiated a study to interrogate the efficacy of SCD inhibition in glioblastoma (GBM), a disease with universal lethality, and to examine the mechanisms of resistance to SCD inhibitors." (PMID 33568479, 2021). "Hypoxia has been shown to increase SCD expression through SREBP-1, and IDH1 mutation increases SCD expression through the oncometabolite D-2-hydroxyglutarate, mainly in low-grade glioma and secondary glioblastoma where these mutations are common." (PMID 37046844, 2023). "SCD expression in glioblastoma tumors may be locally increased, as it is increased by activation of EGFR and platelet-derived growth factor receptor (PDGFR), which activate sterol regulatory element-binding protein 1 (SREBP1) through these receptors." (PMID 37046844, 2023). "SCD expression is reduced in glioblastoma tumors and is often undetectable." (PMID 37046844, 2023). "Consequently, SCD inhibitors may be effective in treating glioblastoma if there is a high expression of this enzyme in the glioblastoma tumor, as shown by experiments in mice." (PMID 37046844, 2023). "Inhibiting the activity of stearoyl-CoA desaturase (SCD), which catalyzes the conversion of SFAs to UFAs, increases SFA levels and subsequently hinders glioblastoma cell proliferation." (PMID 39617788, 2024). "Targeting key lipid metabolism enzymes (SCD, FADS2, ACLY, and ACSL) to re-sensitize cancer cells to chemotherapy has already been demonstrated as a successful approach to combat glioma and glioblastoma." (PMID 38609948, 2024). "Expression data for ELOVL1, ELOVL3, ELOVL6, SCD, and FADS2 were obtained from raw data published in our previous papers, where we examined the expression of elongases and desaturases in glioblastomas." (PMID 37239243, 2023). "Using single cell sequencing data of glioblastoma tissue from patients, we observed that the expression of FASN, SCD and FADS2 correlated with distinct cell fates within the cancer cell cluster." (PMID 36338708, 2022).